ID1 (inhibitor of DNA binding 1)
Diseases named in the same sentence as ID1 in open-access papers (continued):
Sharing a sentence is not in itself a finding about the gene and the disease.
tumor (continued). "However, we found that occasional tumors exhibited Id1+ cells only at the invasive edges of the tumor." (PMID 23691228, 2013). "Id1 and Id3 are considered to have overlapping and synergistic functions in cancer biology and have been related with the inhibition of cell differentiation, cell growth promotion and tumor metastasis." (PMID 23311395, 2013). "Since Id3 was also expressed in these cells and may play a role in the proliferative and/or invasive phenotype of SGCs, it is possible that a double Id1/Id3 knockdown would further increase the reduction of tumor cell aggressiveness." (PMID 23517130, 2013). "This could be indicative of the progression of an invasive tumor cell population that has lost insulin expression, and gained Id1 expression." (PMID 23691228, 2013). "A defect of Id1 in BM could lead to decreased numbers of EPCs in peripheral blood, block tumor angiogenesis, and further suppress tumor development." (PMID 23714001, 2013). "Finally, peritoneal metastases of Id1/Id3 double-knockdown tumor cells were significantly reduced in a mouse model of peritoneal metastasis." (PMID 23311395, 2013). "In our studies, we observed a clear Id1 expression in tumor-derived cells." (PMID 23342268, 2012). "ZNF382 is a tumor suppressor that is ubiquitously expressed in normal tissues, where it recruits KAP1 and causes chromatin compaction and suppression of several oncogenes including ID1." (PMID 21876767, 2011). "Given the poor outcome associated with metaplastic cancer, it may indicate why high ID1 expression in CCND1 low tumours gave the shortest RFS." (PMID 21955753, 2011). "The role of EPCs in tumor neovascularization was studied in an Id1 +/- Id3-/- mouse model which is tumor resistant and has defective angiogenesis, where transplantation of wild type bone marrow to the mutant mice restored tumor angiogenesis and growth." (PMID 21609465, 2011). "We hope that future in vivo application of the peptide aptamer Id1/3-PA7 in tumour-bearing Id1/3 transgenic mice and in Id1+/−Id3−/− knockout mice will give rise to more information regarding its in vivo stability, functional specificity and potential toxicity." (PMID 20842131, 2010). "While the prognosis for the vast majority of NSCLC patients is extremely poor, we note that the primary human tumors evaluated in this study segregated into groups with elevated tumor Id1 expression versus normal tissue and decreased tumor expression versus normal tissue." (PMID 20414347, 2010). "We identify a wide range of Id1 expression patterns in NSCLCs without any notable association of expression level with tumor staging or outcome; however, we do note significant effects of Id1 expression on tumor cell migration in vitro." (PMID 20414347, 2010). "We therefore suggest that Id1 expression in NSCLCs may allow for distinction of NSCLC tumor subtypes which may be specifically responsive to particular forms of therapy targeting Id1." (PMID 20414347, 2010). "Given the key roles that EPCs migration and adhesion may play in tumor metastasis, we tried to investigate the effect of Id1 on circulating EPCs mobilization and recruitment and the possible signal transduction pathways involved in the process." (PMID 20796276, 2010). "Using the monoclonal antibody, Id1 positive cells were detected in tumours at a frequency ∼5–10%." (PMID 20689821, 2010). "In this study we show an essential role for Id1 in EPCs mobilization and recruitment to the tumor." (PMID 20796276, 2010). "This lends further support to the hypothesis that ID1 interferes with centrosomal function and can promote a more aggressive tumor phenotype." (PMID 20070914, 2010). "Therefore, ID-1 is responsible for some changes in gene expression that lead to growth and invasion of tumor cells." (PMID 20003244, 2009).
tumor (continued). "Furthermore, they showed that tumours induce expression of ID1 in EPCs and that suppression of ID1 after metastatic colonisation blocked EPC mobilisation, inhibited angiogenesis and impaired pulmonary macrometastases." (PMID 19491902, 2009). "Like EGFR, Id-1 has been shown to have an up-regulation in many tumours." (PMID 19014499, 2008). "Association between Id-1, EGFR, VEGF, tumour grade and Dukes' stage." (PMID 19014499, 2008). "Those few studies have revealed that Id-1 is involved in tumour progression and associated with poor prognostic factors, but the relationship between Id-1 and EGFR and VEGF has not been studied." (PMID 19014499, 2008). "Therefore, ID-1 has been suggested as responsible for some of the changes in gene expression that lead to increased growth and invasion of tumour cells." (PMID 19002177, 2008). "Non-neoplastic oesophageal epithelium expressed a lower level of Id-1 than the tumour specimens." (PMID 18000500, 2007). "However, a similar tumor growth rate was observed in wild type, p21-/- and Id1-/- p21-/- mice throughout the duration of the experiment." (PMID 18092003, 2007). "We analyzed the frequency of TEMs in Id1-/- mice during tumor growth." (PMID 18092003, 2007). "In addition, a high level of cytoplasmic Id-1 expression was significantly (P=0.045) correlated with T4 stage tumours." (PMID 18000500, 2007). "Overall these observations support the hypothesis that the defect in BM-derived tumor angiogenesis described in the Id1 mutant mice is due primarily to a differentiation failure within the endothelial lineage." (PMID 18092003, 2007). "Id1+/−Id3−/− mice exhibited defects in postnatal angiogenic sprouting and suppressed tumour growth." (PMID 16189517, 2005). "Our data show that Id-1 expression is significantly related with tumour MVD." (PMID 15026801, 2004). "Additional studies are required to determine whether Id-1 has a similar impact on tumour angiogenesis in other human cancers." (PMID 15026801, 2004). "Therefore, taken together with previous studies, our data indicate that Id-1 is an important molecule in tumour angiogenesis and in the aggressiveness of human cancers." (PMID 15026801, 2004). "Therefore, we conclude that compound I-27 may inhibit TNBC tumor angiogenesis through the ID1/TSP-1 signaling pathway." (PMID 40820992, 2025). "Therefore, hyaluronidase may reduce the expression of Id1 and Id3 proteins, potentially helping to mitigate tumor progression." (PMID 41208334, 2025). "Further immunostaining of serial sections revealed high expression of ID1, which plays a role in asymmetric division, of the stem cell marker CD44v6, and of Cre recombinase (marker for the transplanted cells) in the clusters of small, round tumor cells of control mice." (PMID 40316727, 2025). "Therefore, it is necessary to investigate ID1-mediated changes in the tumor microenvironment." (PMID 38658527, 2024). "However, although ID1 is known to regulate intracellular signaling mechanisms in GSCs, its effect on the tumor microenvironment is unknown." (PMID 38658527, 2024). "Additionally, autophagy regulates cancer cell response to chemotherapy through multiple mechanisms beyond ID1 degradation, including cytoprotection, DNA damage response modulation, oxidative stress regulation, and influence on stemness properties and the tumor microenvironment." (PMID 39123206, 2024). "Knockout of Id1 in TAMs showed an inhibitory effect on tumor growth and metastasis in immunodeficient mice, suggesting that ID1 expressing TAMs could affect tumor intrinsic properties." (PMID 37996458, 2023). "Previous studies found that ID1 is upregulated by some tumor-derived factors, such as transforming growth factor beta (TGFβ), in bone marrow-derived myeloid cells to promote the myeloid cell differentiation switch from dendritic cells (DCs) to MDSCs via downregulating Irf8 during tumor progression." (PMID 37996458, 2023).
tumor (continued). "However, the tumor inhibition rate resulting from Id1 depletion in TAMs decreased from ~70% in immunocompetent mice to ~40% in immunodeficient mice, confirming ID1 expressing TAMs in the regulation of T cell-mediated antitumor immunity." (PMID 37996458, 2023). "Such action of ID1 might very well act tumour‐suppressive and protective in vivo." (PMID 34841646, 2022). "In addition, LDN‐212854 inhibited ID1 and EpCAM expression in tumor tissue specimens." (PMID 33834612, 2021). "Furthermore, ID1 is a marker of relatively quiescent glioma stem-like cells that are required for tumourigenesis, are resistant to chemotherapy, and can be responsible for initiating tumour recurrence." (PMID 34205450, 2021). "In addition, Nur77 positively regulated the interaction of Smurf2 and ID1 in splenic tumor tissues." (PMID 33990575, 2021). "Besides tumor cell and epithelium, Id1 is also a functional regulator in other cells." (PMID 33644047, 2021). "The effect of TGFβ on ID1 stabilization may be more significant in tumor development." (PMID 33990575, 2021). "In addition, inhibition of ID1 decreases tumor growth in animal models." (PMID 33324542, 2020). "Loss of Id1 expression might have a negative effect in neovascularization and restore leukocyte adhesion of immune cells trafficking into the tumor microenvironment that is defective in neovessels and thereby enhance the effect of PD-1/PD-L1 axis blockade." (PMID 33126649, 2020). "Interestingly, both ID1 positive and negative cells could be observed, leading to the speculation that ID1 could mark a subpopulation of cells with stemness features in the tumor." (PMID 31013771, 2019). "Id-1 plays important roles in blocking cell differentiation and stimulating cell proliferation by mimicking the activities of other oncogenes, and inhibiting the tumor suppressor activities by targeting the proteins harboring the basic helix–loop–helix (HLH) motif." (PMID 31250351, 2019). "Importantly, our data also showed that VEGFR1 neutralization could suppress tumour growth and metastasis driven by Id1." (PMID 28186102, 2017). "In addition, pre-treatment of lung cell preparations with anti-CXCL5 neutralizing antibody or blockade of its receptor CXCR2 on ESCC cells abrogated the enhanced invasion of ESCC cells attracted by the lung preparations from mice bearing Id1-expressing tumours." (PMID 28186102, 2017). "Furthermore, the reduction of Id1 expression impaired the in vivo tumor-initiating ability of orthotopic xenografts (n = 5; frequency: 1/36,920 cells compared to 1/1,090 cells, P < 0.0001, Poisson distribution), as well as in vivo tumor growth." (PMID 25938540, 2015). "Furthermore, immunohistochemical staining for Id1 followed by Kaplan-Meier survival analysis showed that surgically treated NSCLC patients with high Id1 expression in primary tumor tissues had better disease-free and overall survivals after adjuvant paclitaxel and cisplatin chemotherapy." (PMID 25344919, 2014). "In addition, loss of GCIP through currently unidentified mechanisms during tumor development could also contribute to enhanced Id1 levels, consequently promoting tumor progression of NSCLC." (PMID 24970809, 2014). "In addition, previous studies have also demonstrated that Id1 is required to maintain self-renewal capacity in various stem cells, and is required for tumor initiating function, both in the context of primary tumor formation and during metastatic colonization of the lung microenvironment." (PMID 24970809, 2014). "Interestingly, one tumor showed much higher levels of Id1 (lane #5)." (PMID 23691228, 2013). "Thus, it seems biologically plausible that higher Id1 and Id3 tumor expression levels may reflect the hypoxic status of the neoplasm and therefore would explain the radioresistance observed in those patients." (PMID 23311395, 2013). "Therefore, we suggest that Id1/3-PA7 could represent an exogenous anti-tumour agent that could find applications in targeted therapy." (PMID 20842131, 2010).
tumor (continued). "In addition, by binary logistic regression, we observed that a high nuclear expression of Id-1 in primary ESCC tumours significantly predicted the development of distant metastasis of the corresponding patients within 1 year of oesophagectomy (odds ratio: 4.615, 95% CI: 1.596–13.348, P=0.005)." (PMID 18000500, 2007). "Indeed we show that while the Lin- Flk-1+ cKit+ population is profoundly depleted, three major BM-derived pro-angiogenic hematopoietic cell types (Tie2 expressing monocytes, tumor associated macrophages and neutrophils) are normal in the absence of Id1." (PMID 18092003, 2007). "Transcriptomic analysis and in vivo mouse experiments confirmed that compound I-27 inhibits tumor angiogenesis and induces TNBC cell apoptosis via the ID1/TSP-1 and PI3K/AKT/FoxO1 signaling pathways." (PMID 40820992, 2025). "In TAMs, an inhibitor of differentiation 1 (ID1) prevents CD8+ T cell infiltration and STAT1-mediated transcription of SerpinB2 and CCL4, hence preserving tumor stemness." (PMID 40097979, 2025). "ID1 was markedly overexpressed in PAAD tissues and cell lines, correlating with advanced tumor stage, metastasis, and reduced patient survival." (PMID 40919143, 2025). "Our findings regarding ID1 expression and TGF-B2 transcript counts in the tumour further emphasise its aggressive biology." (PMID 40826447, 2025). "Among them, ID1 and ID3, like ID2, are rapidly degraded via the proteasome and function as oncogenes in certain tumor types." (PMID 40607387, 2025). "Our findings demonstrate that ID1 is not only highly expressed in PAAD but is further induced under hypoxic conditions, correlating with enhanced tumor aggressiveness." (PMID 40919143, 2025). "Our results suggest the ID1 pathway is upregulated in TNBC metastasis to the liver and even higher in metastasis to the lung when compared to primary tumours." (PMID 40116596, 2025). "Collectively, these findings provide the first evidence of post-translational regulation of ID1 by microenvironmental hypoxia via PAAD, offering new insights into tumor adaptation to low oxygen conditions." (PMID 40919143, 2025). "EIF2 signaling is comprised of several endothelial cell transcription factors and regulates both cell cycle progression and angiogenesis, while ID1 signaling activates HIF-1a and VEGF-A to promote tumor angiogenesis in certain cancers." (PMID 38263175, 2024). "It was reported that ATF3 had prognostic significance as a novel tumor suppressor in ESCC, and it can inhibit ESCC through downregulation of ID1." (PMID 39256364, 2024). "Consistent with low WNT signaling in RevCSCs, BLM tumor stem cells had decreased expression of WNT/stemness-related genes compared to Min tumors such as Axin2, Id2, Sox4, Wnt6, Wnt10a, Id3, Prox1, and Id1." (PMID 38893159, 2024). "Specifically, Id1-expressing TAMs have been shown to suppress the antitumour immune response by limiting CD8+ T cell infiltration and function, leading to tumour progression and immune evasion." (PMID 39676870, 2024). "Our discovery suggests that TAMs with high ID1 expression establish a malevolent alliance between the immunosuppressive TME and CSCs to facilitate tumor progression." (PMID 37996458, 2023). "RAW 264.7 cells (shown as RAW-Ctrl) and RAW 264.7 cells with Id1 overexpression (shown as RAW-Id1OE) were stimulated with IFN-γ and LPS to induce the tumor inhibition phenotype." (PMID 37996458, 2023). "The evidence suggested that ID1 inhibits the transcription of SerpinB2 and CCL4 in macrophages to promote tumor immune evasion and augment the tumor-initiating capacity of CRC cells, ultimately resulting in aggravated tumor growth and metastasis." (PMID 37996458, 2023). "Reducing ID1 expression ameliorates CRC progression and enhances tumor sensitivity to immunotherapy and chemotherapy." (PMID 37996458, 2023).
tumor (continued). "Our study revealed that the TME endowed TAMs with high ID1 expression, which interacts with STAT1 to inhibit CCL4 and SerpinB2 transcription, two STAT1 target genes, leading to CD8+ T cell exclusion in tumor sites and cancer stemness traits maintenance." (PMID 37996458, 2023). "By qRT‐PCR analysis of characteristic lung metastasis signature genes, namely ID1 and FSCN1, using the original and tumor derived cell lines, we found that derived cells had higher expression than their parental cell lines." (PMID 37518985, 2023). "Canonical pathways that were significantly enriched included fibrosis signaling, the tumor microenvironment pathway, estrogen receptor signaling, TREM1 signaling, ID1 signaling, STAT3 signaling, and HIF1 signaling." (PMID 38028629, 2023). "We further confirmed the direct interaction between STAT1 and ID1 in HEK 293T cells, RAW 264.7 cells, and CD68+ TAMs in CRC patient tumor tissues by using Co-IP, proximity ligation assay (PLA) and confocal imaging." (PMID 37996458, 2023). "Targeting ID1 and the upstream regulator remarkably rescued the PDAC cell lines from tumor formation related phenotypes in vitro." (PMID 35941362, 2022). "There is also the expression and interaction of immune checkpoint molecules between tumor cells and immune cells to protect cancer cells from the attack of immune cells, such as PD-1, PD-L1, CTLA-4, LAG-3, ID-1 and tim-3." (PMID 35892755, 2022). "GEGFR, CD40, SPATA2, ZBP1, ID1, and MYC showed a significant CNV amplification in most tumour types; however, TLR3, PDHB, FAS, and MAP3K showed a significant CNV deletion in most tumour types." (PMID 36186436, 2022). "In TNBC, ID1 and ID3 are requisite for self-renewal, metastasis, tumor re-initiation, and colonization, making them attractive targets for cancer stem cell therapy." (PMID 36207293, 2022). "Based on our data, we expect that ID1 is increased in response to HIF-targeted inhibitions, and in turn plays a compensatory role supporting the survival, proliferation, and invasion of tumor cells in hypoxia." (PMID 34820369, 2021). "Therefore, silencing ID1 may restore or increase tumor sensitivity to HIF1α inhibition." (PMID 34820369, 2021). "A group of investigators found that deletion of ID1 (inhibitor of DNA binding 1, a helix-loop-helix protein) gene in GBM cells reduced tumor growth and improved sensitivity to TMZ." (PMID 34571991, 2021). "Down-regulation of ID1 expression can not only inhibit EMT formation, but can also induce tumor apoptosis." (PMID 33992097, 2021). "ID1 and ID3 would be necessary for TIC (tumor-initiating cell) functions in the genesis of both primary tumors and metastases, sustaining proliferation via p21." (PMID 34295890, 2021). "We also found GSC stemness-related genes, SOX2 and ID1, and MES subtype-related genes, THBS1 and CD44, enriched in the core of the tumours, together with higher TRIM28 expression." (PMID 34500575, 2021). "Upregulation of the Inhibitor of Differentiation 1 (ID1), in response to tumor-secreted factors, such as TGFβ, is responsible for the switch from DCs differentiation to MDSC expansion during tumor progression and metastasis." (PMID 35003065, 2021). "Only the hypomethylated/upregulated gene ID1 and the hypermethylated/downregulated gene CR1 were both carcinogenic and tumor suppressor genes." (PMID 33833773, 2021). "To establish the in vivo relevance of the increased self-renewal capacity of the Id1/GFP+ tumor cells observed in vitro, we determined the tumor initiating capacity (TIC) of the Id1/GFP+ cells using the limiting dilution assay." (PMID 32766238, 2020). "We performed an immunohistochemical analysis of tumor infiltrating lymphocytes (TIL) from Id1+/+/DPBS (pLKO-sc LLC), Id1+/+/anti-PD1 (pLKO-sc LLC), Id1-/-/DPBS (Id1sh LLC), and Id1-/-/anti-PD1 (Id1sh LLC) tumors." (PMID 33126649, 2020).